ZFP3 (ZFP3 zinc finger protein)
Description:
May be involved in transcriptional regulation.
Synonyms: ZNF752; FLJ30726
Tractability: PROTAC: UniProt records ubiquitination sites on it; ubiquitination databases record sites on it.
Target class: Transcription factor
Gene: Protein-coding gene on chromosome 17 (5,078,467 to 5,096,376, forward strand). Ensembl gene ENSG00000180787.
Subcellular location: Nucleus
Subcellular location (Human Protein Atlas): Cytosol; Nucleoplasm
Gene Ontology:
Molecular function: protein binding; DNA-binding transcription factor activity, RNA polymerase II-specific; RNA polymerase II transcription regulatory region sequence-specific DNA binding
Biological process: regulation of transcription by RNA polymerase II
Cellular component: nucleus
Genetic constraint (gnomAD): Loss-of-function variants: 18 observed, 39.39 expected, observed/expected ratio (o/e) 0.46, 90% interval 0.31 to 0.68. The upper end of that interval is the gene's LOEUF score, 0.68, which puts it in group 2 of 6, group 1 being the genes least tolerant of losing a copy. Missense variants: 495 observed, 632.81 expected, observed/expected ratio (o/e) 0.78, 90% interval 0.73 to 0.84. Synonymous variants: 218 observed, 212.44 expected, observed/expected ratio (o/e) 1.03, 90% interval 0.92 to 1.15.
Homologues: Orthologues: chimpanzee ZFP3 (99% identical), macaque ZFP3 (97% identical), guinea pig ZFP3 (91% identical), rat Zfp3 (87% identical), mouse Zfp3 (86% identical), dog ZFP3 (83% identical). Paralogues in human: ZNF658 (50% identical), ZNF7 (50% identical), ZNF189 (47% identical), ZNF429 (47% identical), ZNF182 (47% identical), ZNF879 (47% identical), ZNF235 (47% identical), ZNF568 (47% identical), ZNF708 (47% identical), ZNF717 (47% identical), ZFP2 (46% identical), ZNF726 (46% identical), and 164 more.
Diseases named in the same sentence as ZFP3 in open-access papers:
ZFP3 is named in the same sentence as 4 diseases in open-access papers, as found by Europe PMC text mining. Sharing a sentence is not in itself a finding about the gene and the disease. The quoted sentences say what the papers report.
heart failure (1 paper, 2023). Inability of the heart to pump blood at an adequate rate to meet tissue metabolic requirements. "ZNF146 and Zfp3 are potential genetic contributors for incident heart failure with reduced ejection fraction." (PMID 37221368, 2023).
lung carcinoma (1 paper, 2025). "ZFP3 is localized to chromosomes 17p12–17pter46, and research reports have demonstrated the prognostic role of ZFP3 in head and neck squamous and lung cancers; however, exploration of its underlying mechanisms is lacking." (PMID 41262242, 2025).
myocardial hypertrophy (1 paper, 2023). "We screened and identified two key proteins, Zfp580 and Zfp3, that play an important regulatory role in myocardial hypertrophy." (PMID 37221368, 2023).
tumor (1 paper, 2021). "In contrast to ERBB2 inhibition, over-expression of ERBB2 in the normal-like ERBB2-negative MCF-10A and MCF-7 tumor line led to increased abundance of phosphorylated ZFP3/ZFP36/TTP protein." (PMID 34535639, 2021).